AKT1 (AKT serine/threonine kinase 1)
Diseases named in the same sentence as AKT1 in open-access papers (continued):
Sharing a sentence is not in itself a finding about the gene and the disease.
glioma (continued). "Upon quantifying the invasion along myelinated nerve fiber projections, we found that glioma cells with high levels of p-AKT1 and ENTPD5 were superior at invading white matter due to an increased protein folding capacity." (PMID 31062076, 2019). "Human AKT1 has been reported previously to induce malignant transformations in various neural cell types in zebrafish leading to glioma growth." (PMID 29465400, 2018). "We also find similar intermediary protein interactions through ESR1, AKT1 and SIRT1, whose activity are also associated with glioma." (PMID 28957313, 2017). "Akt1 is the most well characterized isoform of the three, but in recent years, it has become evident that Akt2 and Akt3 are more important than is Akt1 in glioma development and progression." (PMID 26993778, 2016). "In more recent years, it has become evident that Akt3 is more important than is Akt1 in glioma development and progression." (PMID 26993778, 2016). "In glioblastoma, miR-149 inhibited proliferation and invasion of glioma cells by blocking AKT1 signaling." (PMID 26498692, 2015). "For example, in glioblastoma miR-149 was downregulated and it inhibited the proliferation and invasion of glioma cells by blocking AKT1 signaling." (PMID 23762558, 2013). "We chose glioma as a tumor model because APPL proteins are abundantly expressed in the brain, where they associate with AKT1." (PMID 22989406, 2013). "With respect to brain tumors, the level of AKT1 found in glioma cells and tissues was more similar to that found in normal human astrocytes or non-neoplastic regions of the brain; whereas AKT2 levels were increased, and AKT3 levels were decreased." (PMID 22480225, 2012). "Moreover, analysis of a glioblastoma multiforme (GBM) clinical database indicated that lower expressions of HDAC1, HDAC3, and AKT1 correlated with better overall survival in glioma patients." (PMID 40297576, 2025). "PLK4 expression positively correlates with AKT1 phosphorylation in glioma tissues." (PMID 40940791, 2025). "Consistently, a low level of AKT1 mRNA predicted poor prognosis in glioma patients." (PMID 38669103, 2024). "Coimmunoprecipitation confirmed that PDZK1 interacts with AKT1 in glioma cells." (PMID 38669103, 2024). "In glioma, inhibition of AKT1 phosphorylation at Ser473 has been reported to inhibit GBM invasion." (PMID 39458959, 2024). "To determine whether PDZK1 can mediate the cell cycle in glioma cells by interacting with AKT1, we used flow cytometry to investigate the effects of PDZK1 on cell cycle progression." (PMID 38669103, 2024). "The results showed a negative correlation between AKT1 methylation and AKT1 gene expression in glioma tissues (P < 0.001), indicating that AKT1 gene expression may be epigenetically regulated." (PMID 38835342, 2024). "In glioma, miR-637 represses tumor cell proliferation and migration by targeting Akt1." (PMID 36329557, 2022). "Circ-CFH promotes glioma growth via miR-149 sponging and AKT1 signaling pathway regulation." (PMID 35883576, 2022). "Downregulating or inhibiting phosphorylation of Akt1 and NF‐κB‐p65 could lower glioma cell proliferation." (PMID 37786890, 2022). "In addition, IL-17 can promote the proliferation and migration of glioma cells by activating the PI3K/Akt1/NF-κB-p65 pathway." (PMID 36119086, 2022).
glioma (continued). "Western blotting revealed that the expression levels of p-PI3K and p-AKT1 in glioma cells treated with OSW-1 were significantly lower than those in the controls; however, 740Y-P, a PI3K activator, significantly reversed the inactivation of the PI3K/AKT signaling pathway caused by OSW-1." (PMID 36133816, 2022). "AKT1, MTOR, CCND1, and EGFR are closely associated with autophagy and apoptosis in glioma." (PMID 35140796, 2022). "Moreover, AKT1 can be regulated by miR-149 in glioma, and thus represents a promising target for glioma treatment." (PMID 35013126, 2022). "Furthermore, it was indicated that miR-637 has a tumor suppressor role, which prevents migration and invasion of cancer cells by suppression of AKT1 in human glioma." (PMID 33541259, 2021). "Finally, using the glioma cohort from the Shanghai Changzheng, we determined that AKT1 and SERBP1 display good expression correlation based on immunostaining." (PMID 32762776, 2020). "Moreover, the overexpression of Akt1 and 2 isoforms have been reported in many other cancers such as breast, liver, lung, glioma, and neuroblastoma." (PMID 31252679, 2019). "Since AKT signaling is often upregulated in gliomas due to genetic alterations of PI3 K or PTEN, we investigated whether AKT1-driven ENTPD5 expression is required for glioblastoma cells to produce SPARC." (PMID 31062076, 2019). "Interestingly, in a recent study, the Akt1 isoform was unable to induce PDGF-dependent high-grade glioma in a genetically engineered tumor model, whereas Akt2 and Akt3 isoforms strongly promoted high-grade glioma progression." (PMID 29562639, 2018). "In addition, AS1411 inhibited the migration and invasion of glioma cells in an Akt1-dependent manner." (PMID 27907160, 2016). "For example, the expression of miR-149 was down-regulated in glioblastoma and it could restrain the proliferation and invasion of glioma cells through hindering AKT1 signaling." (PMID 26269151, 2015). "Similarly, overexpression of KRASG12V in a putative neural stem and/or progenitor cells induced brain tumorigenesis and overexpression of dominant-active human Akt1 (DAAkt1) or Rac1G12V (DARac1) (Ptf1a promoter)-induced gliomas of various histological grades, frequently infiltrated." (PMID 35706426, 2022). "Besides, AKT1, JUN, ALB, MAPK1, and TNF display good diagnostic value in glioma." (PMID 34873410, 2021). "Furthermore, it was cytotoxic against Akt1-knockout A172 glioma cells." (PMID 33159013, 2020). "Indeed, this concept was tested in one approach, which combined the lysosomotrophic agent chloroquine (CQ) that blocked the activity of lysosomal proteases, with the PI3K/mTOR/AKT inhibitors (AKT-1/2 and PI-103), resulting in the overall potentiation of glioma cell death." (PMID 32517694, 2020). "The mRNA expression of HDAC1, HDAC2, HDAC3, HDAC6 and PI3K/AKT1 was analyzed in GBM and low grade glioma tissues." (PMID 40297576, 2025). "Immune-related pathways such as TNF signalling (IDH3B/G, MDH1, ACO2, SDHA, OGDHL) and JAK/STAT3 (PIAS2/3, PTPN2, AKT1/2, MCL1, CISH, AOX1) signalling are enriched in gliomas and play a critical role in their progression." (PMID 41007296, 2025). "The overall survival time of glioma patients with low HADC1, HDAC3 and AKT1 expression is better (p < 0.05)." (PMID 40297576, 2025). "The group cutoff was selected as the median to divide the high expression group and the low expression group (cutoff-high = 50%; cutoff-low = 50%) for analyzing the mRNA expression of AKT1 and MAPK1 in glioma to verify their prognostic relationship." (PMID 38835342, 2024).
glioma (continued). "To investigate the relationship between AKT1 and MAPK1 mRNA expression and clinicopathologic parameters, we used the CGGA database, which comprises 325 cases from the glioma mRNA microarray database, for correlation analysis." (PMID 38835342, 2024). "Overall, our study revealed that PDZK1 acts as a novel oncogene in glioma by binding to AKT1 and maintaining the activation of the AKT/mTOR signaling pathway." (PMID 38669103, 2024). "The mRNA expression levels of AKT1 and MAPK1 were significantly different between normal and glioma tissues." (PMID 38835342, 2024). "Consistent with previous findings, we observed that the overexpression of CLEC19A significantly suppressed the proliferative potential of glioma cells through the inhibition of PI3K, AKT1, and NF-κB." (PMID 38167030, 2024). "AKT1 and MAPK1 mRNA expression levels were significantly different in tumor and normal tissues in gliomas (P < 0.05)." (PMID 38835342, 2024). "The researchers found that miR-124-3p targeted the flotillin 2 (FLOT2) gene in gliomas, suppressing FLOT2 expression and affecting the AKT1 pathway." (PMID 39450275, 2024). "The mRNA expression levels of AKT1 and MAPK1 were relatively high in glioma, while those of RXRα, ESR1, and HSP90AA1 were relatively low." (PMID 38835342, 2024). "AKT is an established oncogenic kinase with at least three mammalian isoforms AKT1/PKBα, AKT2/PKBβ, and AKT3/PKBγ of which AKT2 plays major pro-oncogenic roles in cancers, including glioma." (PMID 36120909, 2022). "Therefore, we speculated that the anti-glioma mechanisms of OSW-1 might be associated with inactivation of the PI3K/AKT signaling pathway by decreasing the relative levels of phosphorylated PI3K and AKT1." (PMID 36133816, 2022). "The AKT family is divided into three isoforms, namely, AKT1, AKT2, and AKT3, but only AKT3 is described as mandatory for the transformation of astrocytes into glioma cells." (PMID 35004666, 2021). "Our results confirm reported investigations and show that AKT1 and AKT2 act as promoters of glioma tumorigenesis, while AKT3 shows a tumor-suppressor role." (PMID 34209611, 2021). "By target harvesting, six core genes including AKT1, JUN, ALB, MAPK3, MAPK1, and TNF were screened from a total of 205 targets of luteolin against the glioma network." (PMID 34873410, 2021). "AKT1 is a crucial component of AKT signaling that contributes to the proliferation, migration, and invasion of multiple tumor types including glioma 22-27." (PMID 34475988, 2021). "AKT1 is a key mediator of the PI3K-Akt signaling pathway and is involved in cellular function regulation in various tumors, including gastric cancer, glioma, lung cancer, and esophageal squamous cell carcinoma." (PMID 34149863, 2021). "Akt1 physically interacts with UBE2S and phosphorylates UBE2S at Thr152 in glioma cells, which is important for stabilization of UBE2S." (PMID 34123793, 2021). "More importantly, AKT1, JUN, MAPKs, and TNF contribute to resistance to chemotherapy and radiotherapy, one of the greatest barriers in the treatment of glioma." (PMID 34873410, 2021). "The anti-tumor activity of miR-149 in glioma cells was found to be correlated with low-expression of PCNA, p-AKT1, cyclin D1, and MMP-2." (PMID 31297133, 2019). "Similar results were observed in glioma tissue samples, the expression levels of TCRP1 has a positive correlation with p-PDK1 (r values=0.5729), or p-AKT1 (r values=0.7802), respectively." (PMID 28436990, 2017). "In the present study, we investigated the effects of CHL1 on proliferation indexes and activation of Akt1 and Erk signaling by siRNA in U-87 MG human glioblastoma and human U251 and SHG-44 glioma cells." (PMID 29089868, 2017). "Decreases in Akt1 levels mediate EMT and effect cell cycle by regulating proteins such as Foxo1, MMP2, p27Kip1 and p21Cip1 in cervical carcinoma and glioma." (PMID 27323412, 2016).
glioma (continued). "They identified Akt1 as a substrate of PLK4, which promoted glioma cell proliferation and invasion." (PMID 41488365, 2025). "In our study, we found that PDZK1 formed a complex with AKT1 in glioma, suggesting that PDZK1 could directly affect the function of AKT1." (PMID 38669103, 2024). "Taken together, our results revealed that PDZK1 interacted with AKT1 and that knockdown of PDZK1 may inhibit the activation of the AKT-mTOR signaling pathway in glioma cells." (PMID 38669103, 2024). "Moreover, AKT1 and MAPK1 mRNA were expressed at a high level in glioma, according to the clinical database analysis results." (PMID 38835342, 2024). "Moreover, in two glioma cell lines, RNF139 overexpression inhibited, whereas RNF139 knockdown enhanced the phosphorylation of phosphatidylinositol 3-kinase (PI3K) and AKT serine/threonine kinase 1 (AKT)." (PMID 34106407, 2021). "The tissue microarray results showed that RIOK1 and AKT1 expression in glioma tissues were significantly higher than those in matched normal brain tissues." (PMID 34475988, 2021). "Lower grade gliomas, the AA group, harbored the highest number of CNA in genes PTEN (50%), PIK3AP1 (49%), and CHUK (49%), while the DA group carried the highest number of CNA in genes AKT1 (15%), AKT2 (11%), and GSK3β (11%)." (PMID 34209611, 2021). "The confirmation of Th17 cell infiltration in the glioma tissues gives rise to the investigation of the role of IL-17, one of the major mediators and hallmarks of the Th17 cells, which promotes glioma proliferation and migration through the activation of PI3K/Akt1/NF-κB-p65 axis." (PMID 34671362, 2021). "Thus, AKT1 and AKT2 were considered as valuable targets for glioblastoma therapy as well as a rational strategy for restraining the metastasis of gliomas." (PMID 29890617, 2018). "Likewise, AKT1 and AKT2 found to be related to bcatenin/Tcf-4 signaling pathway that promoted malignant transformation in human LN229 glioma cell line." (PMID 29890617, 2018). "This assumption is supported by a recent study in a murine glioma model showing that overexpression of Akt1 WT failed to significantly modulate the expression of proteins associated with DNA DSB repair and radiosensitivity." (PMID 28209968, 2017). "The suppression of the expression of Akt1 by AS1411 suggests that AS1411 may reduce the glioma invasiveness and metastasis." (PMID 27907160, 2016). "These miR-637-targeted genes include HMGA1, CDK6, and WNT7A in glioma, HEMGN in PTC, APLN in GC, USP21 in HCC, LY6E and CTSB in CHOL, NUPR1 in OSCC and MM, HDAC4 in SaOS, ABL1 in CML, KLK4 in OC, PLXNB2 in OC, AKT1 in TNBC, PTC, and HCC, AKT3 in TNBC, and RING1 in CCa." (PMID 36175921, 2022). "For instance, miR-422a was confirmed to inhibit glioma cell proliferation, invasion, and migration by targeting PIK3CA, which is a critical member of PI3K/Akt signal pathway; miR-422a was proven to directly target AKT1 to inhibit PI3K/Akt pathway and colorectal cancer cell proliferation." (PMID 34715879, 2021). "Based on the TCGA data, we confirmed that AKT2, but not AKT1 or AKT3, interacts with PDCD4, thus leading to the suppression of PDCD4 in glioma cells." (PMID 33304903, 2020). "Taken together, these data suggest that AKT2, but not AKT1 or AKT3, interacts with and suppresses PDCD4 in the glioma cells." (PMID 33304903, 2020). "Here, we present evidence that AKT2, but not AKT1 or AKT3, interacts with PDCD4 leading to its suppression in glioma cells, and is consistent with the inverse relationship between mRNA levels of AKT2 and PDCD4 observed in the TCGA data analysis." (PMID 33304903, 2020).
glioma (continued). "Similarly in a PDGFB-driven mouse model of low-grade glioma, transgenic expression of AKT2 or AKT3 but not AKT1 greatly accelerated tumour formation." (PMID 28082369, 2017).
ovarian carcinoma (459 papers, 2008 to 2026). A malignant neoplasm originating from the surface ovarian epithelium. "Recently, miransertib (ARQ 092) an oral, allosteric, selective pan-AKT inhibitor was identified, trialled in patients with ovarian cancers bearing an activating AKT1 variant and reported showing favourable efficacy and side effects." (PMID 40426219, 2025). "In ovarian cancer, the upregulation of AKT1 and VEGFA is associated with proliferation, metastasis, and angiogenesis." (PMID 38666020, 2024). "In cisplatin-resistant ovarian cancer, a study investigated the relationship between AKT1, ferroptosis susceptibility, and autophagic degradation of FTH1." (PMID 38562143, 2024). "Protein kinase B (Akt1), which is a recurrently mutating somatic gene in breast, lung, and ovarian cancer, is a key factor in cancer cell survival, migration, and metastasis." (PMID 37894581, 2023). "In this study, elevation of HK2 in human ovarian cancer cells significantly promoted cell growth and motility capacity, and further study implied that active of Akt1 in HK2-modified cells must associated with the enhanced cell proliferation and motility." (PMID 35953860, 2022). "The transforming E17K PH domain mutation that occurs in AKT1 is confirmed to be associated with breast, colorectal and ovarian cancers." (PMID 35522942, 2022). "Other notable findings include that ESR1 mutations in cluster 1357.1 are associated with high ESR1 in ovarian cancer, whereas AKT1 mutations in cluster 756.0 are associated with high AKT1 proteins." (PMID 33875650, 2021). "The W80R mutation in the PH domain of AKT1 had been reported to cause ovarian cancer by in-vitro studies and recorded in the Cancer genome database." (PMID 34727985, 2021). "Some somatic mutations in the AKT1 gene are reported to be associated with various cancers, including breast, colorectal and ovarian cancers." (PMID 34634811, 2021). "Akt1 overexpression and Akt2 gene amplification caused ovarian cancer cells more highly resistant to paclitaxel." (PMID 28938696, 2017). "According to the Catalogue of Somatic Mutations in Cancer (COSMIC) database (version 62), the AKT1 E17K hotspot mutation is present in approximately 4% of breast tumors, 2.5% of endometrial cancers and 0.3% of ovarian cancers." (PMID 28472036, 2017). "A mutation in AKT1 has been implicated as cancer causation in breast, colorectal and ovarian cancers in humans." (PMID 29207666, 2017). "The somatic mutation of AKT1 isoform associated with the substitution of glutamic acid by a lysine at amino acid 17 (E17K) of AKT1 has been reported in human breast, colorectal, ovarian cancers, and lung squamous cell carcinoma." (PMID 29299162, 2017). "Mutations in Akt1 that result in constitutive activation or elevated Akt1 expression have been implicated in a wide range of cancers, including colorectal, breast, prostate, lung, pancreatic, liver, and ovarian cancers as well as in leukemia and glioblastomas." (PMID 23342113, 2013). "AKT1 is mutated in 2 to 8% of breast, 6% of colorectal and 2% of ovarian cancers samples examined in one study." (PMID 21422497, 2011). "A recurrent somatic mutation, E17K, in the pleckstrin homology domain of the AKT1 gene, has been recently described in breast, colorectal, and ovarian cancers." (PMID 18611285, 2008). "Recently, a research group discovered a recurrent somatic mutation of AKT1 gene in human breast, colorectal and ovarian cancers." (PMID 18392055, 2008). "An earlier study discovered an oncogenic AKT1 gene mutation (AKT1 E17K) in breast, colorectal and ovarian cancers." (PMID 18392055, 2008). "AKT2, a homolog of AKT1, could encode a serine/threonine protein kinase which is largely amplified in pancreatic and ovarian cancers." (PMID 38310291, 2024).